CASP8 (caspase 8)
Diseases named in the same sentence as CASP8 in open-access papers (continued):
Sharing a sentence is not in itself a finding about the gene and the disease.
infection (continued). "Infection-induced caspase-8 activation also occurred with strain BA199 of L. amazonensis, but was absent with strain M1176 of L. guyanensis, corroborating the idea that induction or non-induction of apoptosis are features associated with the species." (PMID 26513474, 2015). "For the periods evaluated, activation peaks at 18 or 14–18h post-infection for caspase-8 and caspase-9, respectively." (PMID 26513474, 2015). "The typical markers of apoptosis FLIP was found decreased by the infection which can be rationalized as a response aimed to increase the amount of activated caspase 8 by reducing the inhibiting effect of FLIP on its processing." (PMID 26091359, 2015). "Western blot analysis for apoptotic protein in brain homogenates revealed that apoptotic proteins caspase-8, -3, and -9 and cytochrome C increased post-infection." (PMID 25890054, 2015). "The degradation of pro-caspase 8 in IAVs infected cells was weak at all times after infection and was only a little stronger than in mock-treated control cells." (PMID 24923273, 2014). "The activation of caspase 8, in addition to caspase 3 and caspase 9, was investigated in response to infection with EV71." (PMID 25350381, 2014). "After CA16 infection, caspase 8 and caspase 9 activities first increased and then decreased from 36 h post-infection in RD and SK-N-SH cells or from 24 h post-infection in A172 cells." (PMID 25350381, 2014). "In A172 cells, activation of caspase 8 and caspase 9 was noted at 12 h post-infection, and caspase 3 at 36 h post-infection." (PMID 25350381, 2014). "We then tested if infection also affects signaling upstream of the executioner caspase i.e. caspase-9 and caspase-8 processing or activity, respectively." (PMID 21799887, 2011). "Further analyses demonstrated that upregulation of cleaved caspase-8 and Bcl-2 expression was minimal, but expression levels of cleaved caspase-9, Bax and cytoplasmic cytochrome C increased in both cells after the infection." (PMID 21952623, 2011). "It was observed that the levels of IPS-1, TRAF 6 and active Caspase 8 were significantly increased both after 12 and 24 h post infection, whereas the levels of phosphoIKKα/β and FADD were only increased after 24 h (p<0.05)." (PMID 21738791, 2011). "As the primary activation of caspase-8 is due to receptor binding, it was expected that caspase-8 activation would occur relatively early after infection with BTV." (PMID 21134281, 2010). "AdTRAIL infection induced caspase-8 and Bid cleavage, which was enhanced upon combined treatment with chemo (radio) therapy in H460 cells." (PMID 15173860, 2004). "The infection activates caspase-9 and caspase-3, but not caspase-8, and causes mitochondrial damage, indicating apoptosis via the mitochondrial pathway." (PMID 41701783, 2026). "Tnfr1 deficiency and TrifLps2 mutation protected macrophages from cell lysis at 3 h (Fig. EV1C) and 5 h post-infection and these cells displayed reduced cleavage of caspase-8, caspase-3, GSDMD as well as the fluorogenic caspase-3/7 substrate (Fig. EV1D) compared to WT macrophages." (PMID 40128366, 2025). "Importantly, SARS-CoV-2 infected R3-/- vs. WT comparisons revealed distinct signatures compared to SARS-CoV-2 infected C8/R3-/- vs. infected WT comparisons, indicating that caspase-8 exerts effects independently of RIPK3 during infection." (PMID 41233351, 2025). "Following infection, caspase-8 protein levels increased, particularly in regions adjacent to nucleocapsid-positive cells, whereas CC3 (activated caspase-3) levels remained comparable to uninfected controls, suggesting that caspase-8 activation was not accompanied by widespread apoptotic cell death." (PMID 41233351, 2025). "Downstream apoptotic mediators caspase-8 and caspase-3 were also upregulated upon infection." (PMID 41294830, 2025).
infection (continued). "qRT-PCR analysis revealed that gcHnf4α overexpression upregulated the mRNA levels of apoptosis-related genes—aif, caspase 3, caspase 8, caspase 9, bax, and bcl-2—during A. salmonicida mono - infection, indicating potential engagement of both pro- and anti-apoptotic pathways." (PMID 40920830, 2025). "rVSV-NDV infections in caspase-8 knockout cells have shown that syncytial oncolysis remained unimpaired (A549) or could even be potentiated (H1437), which argues for a potential switch to necroptosis." (PMID 40896365, 2025). "However, even though C. trachomatis-infected cells are protected from apoptosis in early and mid-infection, they can still die by another type of cell death, which is caspase-8-dependent and resembles necrosis." (PMID 41204030, 2025). "At the molecular level, either wtVSV or VSV-S infection led to the appearance of cleaved caspase 3, caspase 8, and N-terminal gasdermin E (GSDME-N), supporting the notion that VSV can trigger caspase 3/8/GSDME-dependent pyroptosis regardless of SMAC/DIABIO insertion." (PMID 39789615, 2025). "Consistent with our previous studies demonstrating HCMV prevents the intrinsic biological programming of monocytes to activate extrinsic apoptosis, infection increased the levels of procaspase-8 with a corresponding decrease in the formation of the cleaved forms of caspase-8 (14 kDa and 18 kDa)." (PMID 41190811, 2025). "Additionally, infection with Yptb WT resulted in significantly elevated mRNA levels of Tnfa, Caspase 8, and Caspase 3 in mouse intestines, whereas these levels were substantially reduced in the ΔtkeA‐infected mice." (PMID 40365777, 2025). "Therefore, moDCs were infected with both strains and caspase-8 activity was assessed at different time points of infection." (PMID 38408992, 2024). "Notably, in the presence of caspase-8 as well as pan-caspase inhibitors, the levels of IL-18 increased in response to 5448AP infections, reaching the levels of 5448 infection control." (PMID 38408992, 2024). "Additionally, there was a higher level of the active caspase-8 (p18) in infection with WT or ΔPldA-in than with ΔPldA." (PMID 39369445, 2024). "As is the case with MDS patients, we found that Casp8−/− mice are vulnerable to infections." (PMID 38637559, 2024). "Loss of RIPK3 or ZBP1 or the combined loss of either with a non-cleavable Caspase-8 would drive unsustainable IAV replication leading to lethal infection, compromising host viral defense and as a consequence of apoptosis and necroptosis inhibition." (PMID 36175538, 2023). "Indeed, C. rodentium infection of Casp8–/–Ripk3–/–Casp1–/– mice recapitulated the infection-induced lethality of Casp8–/–Ripk3–/–Casp1/11–/– mice, while both Casp8–/–Ripk3–/–Casp11–/– and Casp8–/–Ripk3–/–Gsdmd–/– mice survived the infection." (PMID 37080966, 2023). "Alternatively, gasdermin-independent restriction of L. pneumophila may be a result of compensatory caspase-8-mediated apoptosis, which is in line with the gasdermin-independent cell death we observe occurring late during infection." (PMID 37279255, 2023). "The expression profiling of TLR signaling pathway genes after pathogen stimulation showed that the infection of pathogens induced the activation of (TLR1-2) - MyD88 - FADD - Caspase 8 involved signaling pathway, and inhibits the spread of bacteria in the body through cell apoptosis." (PMID 37056759, 2023). "Finally, we assessed how inadequate intestinal C. rodentium clearance in Casp8–/–Ripk3–/– mice impacted on its systemic presence by quantifying splenic pathogen loads at distinct stages of the infection." (PMID 37080966, 2023). "Likewise, caspase-8 is involved in initiating extrinsic apoptosis to facilitate host defense via death receptors of the TNF family against pathogen infection." (PMID 36979955, 2023). "However, there were only minor changes in Caspase-8 levels during infection, demonstrating that mitochondrial-mediated apoptosis is the predominantly targeted for inhibition." (PMID 37594275, 2023).
infection (continued). "In conclusion, the experiments carried out in this study have allowed to gather new information on the key role of caspase-8 in modulating the cross-talk between apoptosis and autophagy and hence the outcome of infections in cells prone to apoptosis when exposed to HSV-1." (PMID 36418547, 2023). "This illustrates the dynamic nature of inflammatory responses during C. rodentium infection, as additional IL-22 analyses in Casp8–/–Ripk3–/– mice at 7 dpi revealed that these mice produced less IL-22 than their Casp8+/-Ripk3–/– littermates at this stage of the infection." (PMID 37080966, 2023). "Interestingly, executioner caspase-3/7 activity is significantly lower at 3 h post-infection for WT compared to ∆eseN, presumably because of the suppression of caspase-8 at 1 and 3 h PI by EseN." (PMID 37796003, 2023). "Interestingly, caspase-8, -9, and -3/7 levels induced by P/V/F mutant infection were significantly higher in 22Rv1 cells compared to BPH-1 cells at late times post-infection." (PMID 35631014, 2022). "Altogether, TNF-α elicited RIP1/FADD/caspase-8-mediated apoptosis of astrocytes upon AC infection." (PMID 33683530, 2022). "Furthermore, the interaction between RIP1 and FADD/Caspase-8 was notably enhanced after AC infection." (PMID 33683530, 2022). "However, we have found that the activity of these caspases is dispensable for IFN regulation during KSHV lytic infection, and that caspase-8 is likely the key regulator." (PMID 36255240, 2022). "Similarly, co-deletion of ASC or caspase-8/RIPK3 with caspase-1/-11 phenocopies NLRC4 deletion during challenge with flagellin or infection with Legionella." (PMID 35563804, 2022). "Furthermore, ORFV NA1/11 infection also significantly increased the levels of caspase 3/7 and caspase 8 activities in both A549 and LLC cells." (PMID 35959371, 2022). "Altered splicing of inflammatory and immune genes (e.g., IRAK4, MAP3K7, and CASP8) due to spliceosome mutations may contribute to MDS pathogenesis by leading to inflammation, changes in immune cell function, and increased risk of infection." (PMID 34196950, 2022). "In the later stages of infection, macrophages underwent caspase-8-independent apoptosis characterized by activation of caspase-9 and caspase-3/7, suggesting intrinsic apoptosis can also be activated during B. thailandensis infection, consistent with previous reports." (PMID 34154417, 2021). "In wt cells, MVA-infection induced strong cleavage of caspase-8, caspase-9, and caspase-3." (PMID 34711816, 2021). "To evaluate the temporal aspects of PCD suppression by vIRA, vICA, vMIA and vIBO, we compared the parental virus to M45mutRHIM (inducer of RIPK3-dependent necroptosis), ∆M36 (inducer of CASP8-dependent apoptosis), and ∆M38.5/M41.1 viruses during infection of WT macrophages." (PMID 34578288, 2021). "We speculate that upon infection of hMDM with T3SS/flagellin-deficient S. Typhimurium, IL-1β and IL-18 are processed in a caspase-8–dependent manner and released in a GSDMD-independent way." (PMID 33380493, 2021). "Therefore, vICA-mediated inhibition of CASP8 is crucial during the early stages of infection where TNF signaling represents the most prominent inflammatory pathway leading to CASP8 activation." (PMID 33126536, 2020). "At the early stages of infection inducing apoptosis of infected cells via increasing caspase-8 activity, using small molecules or triggering apoptosis via TRAIL receptor agonists might be beneficial." (PMID 33072409, 2020). "We also knocked down caspase 8 by siRNA prior to CtBP shRNA infection, and analyzed cell viability." (PMID 32332713, 2020).
infection (continued). "Thus, during infection, vICA mitigates CASP8-driven macrophage death as well as inflammatory signaling." (PMID 33126536, 2020). "In addition, infection with P. vivax induced expression and cleavage of caspase-8 in circulating CD14+ monocytes." (PMID 32929083, 2020). "However, initiator caspase-8 activity increased only in HOS cells after infection and only at higher virus load (>10 virus particles per cell)." (PMID 31969562, 2020). "Therefore, inducing extrinsic apoptosis and caspase-8 activation via targeting c-FLIP or caspase-8 at the beginning of the infection seems to be an important strategy to inhibit virus replication, and limit the number of viruses." (PMID 33072409, 2020). "CASP8 is a central innate immune defense mediator against MCMV even though this caspase only makes a modest contribution to an effective antiviral T cell response that brings infection under control." (PMID 33126536, 2020). "However, during infection type I IFNs mediated HSPC death by reducing caspase 8 expression and activity, which correlated with reduced RIPK1 and RIPK3 cleavage in the BM." (PMID 30080899, 2018). "The striking increase in full length pro-caspase 8, as well as active caspase 8, in Ifnar1-/- mice was apparent prior to infection, suggesting Ifnar1-/- mice may be poised to resist RIPK1-dependent cell death." (PMID 30080899, 2018). "We hypothesized that 3Cpro interacts with RIPK1 or TRIF, and thereby cleaves the death kinase RIPK1, and corrupts caspase-8 activation at late stages of infection." (PMID 29449668, 2018). "Later during infection, when numerous virions have been produced within the infected cells (high moi), the pro-apoptotic signals e.g. enhanced caspase-8 gene expression are activated and result in the lyse of the infected cells with release of the newly produced virions." (PMID 30135434, 2018). "Caspase-8 may be critical for monocyte-to-macrophage differentiation, thus there may be a complex interplay between pUL36 and caspase-8 in long term infection of myeloid cells and HCMV persistence." (PMID 30274264, 2018). "How type I IFNs regulate caspase 8 during infection is an important and open question." (PMID 30080899, 2018). "In addition, we also found that caspase-8 was activated during the infection, and in the caspase-8 inhibited macrophages, the ratio of apoptosis, the cleavage of Bid, and the release of AIF and EndoG from mitochondria were significantly decreased." (PMID 29184851, 2017). "Our data suggest that caspase-8 activation in the Naip5/NLRC4/ASC inflammasome may favor host responses during infections against pathogens that inhibit components of the pyroptotic cell death including caspase-1 and gasdermin-D." (PMID 28771586, 2017). "It is possible, however, that caspase-8 may induce cell death in response to infection by other mechanisms." (PMID 27670879, 2016). "Next, the activities of caspase 8 and caspase 9 on infection with either H37Ra or H37Rv were monitored at 24 hrs of infection, using calorimetric assay, and we found that the expression level of caspase 8 was reduced to 50% (0.8 ± 0.3) in host cells infected with H37Rv." (PMID 25785198, 2015). "Upon SVCV infection, CASP8 was up-regulated more than 2 times." (PMID 25344771, 2014). "Interestingly, we observed a significant activation of caspase 9 on day 1 post infection, while caspase 8 was shown to be activated from day 2 post infection." (PMID 24034452, 2013). "HIV-1 could, for example, delay or prevent apoptosis through TAR miRNA-mediated downregulation of Caspase 8 early in the infection cycle, to ensure robust viral replication and packaging." (PMID 23938024, 2013). "To study the effect of CDV infection in HeLa cells, we examined apoptotic markers 24 h post infection (pi), by flow cytometry assay for DNA fragmentation, real-time PCR assay for caspase-3 and caspase-8 mRNA expression, and by caspase-3 and -8 immunocytochemistry." (PMID 21718481, 2011).
infection (continued). "Interestingly, while caspase-9 processing was blocked, caspase-8 activity was even increased by infection with Simkania, demonstrating the selective inhibition of caspases in cells infected with Simkania." (PMID 21799887, 2011). "To determine whether apoptosis was mediated by extrinsic or intrinsic pathways we exposed lymph node cells from progressor animals taken at week 12 post infection to small molecule inhibitors of caspase-8 or caspase-9, respectively." (PMID 21203477, 2010). "Caspase-8 cleavage is apparent in infected cells around 24 h post infection." (PMID 19936232, 2009). "In addition, infection can activate caspase 8 directly through the innate immune system via toll-like receptors (TLRs) and the adaptor molecule MyD88." (PMID 20069051, 2009). "In addition, even infection of macrophages with the classical RIPK1/caspase-8–activating pathogen, Yersinia pseudotuberculosis, sensitized TBK1/IKKε-inhibited cells to enhance RIPK1/caspase-8 activation and death but also enhanced secondary caspase-1 activation." (PMID 40053580, 2025). "To assess whether the BM failure that developed in Casp8−/− mice was due to the propensity of Casp8−/− HSPCs to suffer infections or inflammation-induced cell death, we compared the responses of Casp8−/− and WT HSPCs to low-dose TLR agonists or inflammatory cytokines." (PMID 38637559, 2024). "Therefore, we assayed cell death and caspase-1 processing in Casp8D387A/D387A BMDMs, which express an uncleavable caspase-8, either after infection with Yptb or treatment with lipopolysaccharide (LPS)/IKK inhibitor (IKKi), which pharmacologically mimics the activity of YopJ." (PMID 39058785, 2024). "Indeed, post-infection time-course RNA-seq analysis showed an upregulation of Casp3 but also a number of other genes involved in apoptosis and necroptosis such as Stk24, Akt1, Madd, Casp7, and Casp8 peaking at 5 and 6 dpi." (PMID 38009950, 2024). "However, caspase-8 expression was found to be reduced at 72 h in infection EVs compared to control EVs, and the reduction could suggest the inhibition or delay of apoptosis and the CRFK cell survival after CoV infection over time." (PMID 36979955, 2023). "Finally, although caspase-8 deficiency leads to higher C. rodentium shedding at 15 days post-infection, it is not known how the innate immune system guarantees host defense against C. rodentium in conditions of impaired caspase-8 signaling." (PMID 37080966, 2023). "Therefore, the investigated deletion of six nucleotides in the CASP8 promoter may provide genetic protection to their carriers against infection and high parasite density by promoting the survival of T cells, increasing the efficiency of the immune response." (PMID 37794476, 2023). "Differential regulation of CASP8 and MAP2K3, two genes involved in the activation of MAPK14/p38, was observed, which could explain differences in the pro-inflammatory responses observed after infection with highly and less pathogenic ASFV isolates." (PMID 36298696, 2022). "Thus, it has been recently described that GSDME, a protein related with pyroptosis and IL-1β release, is activated in neutrophils in a RIPK1-dependent manner and that the FADD-RIPK1-caspase 8 complex is recruited after infection to cleavage GSDMD and initiates the inflammatory cell death." (PMID 35716229, 2022). "At 24 h after infection, the following genes were upregulated in infected macrophages transfected with the let-7e inhibitor compared to macrophages transfected with NC: Tlr7, Ly96/MD-2, Casp8, Map3k1, Mapk8, Ptgs2/Cox2, Csf 3/GCSF, and the ubiquitin-conjugating enzyme E2N (Ube2n)." (PMID 30555476, 2018).